RYK (receptor like tyrosine kinase)
Description:
May be a coreceptor along with FZD8 of Wnt proteins, such as WNT1, WNT3, WNT3A and WNT5A. Involved in neuron differentiation, axon guidance, corpus callosum establishment and neurite outgrowth. In response to WNT3 stimulation, receptor C-terminal cleavage occurs in its transmembrane region and allows the C-terminal intracellular product to translocate from the cytoplasm to the nucleus where it plays a crucial role in neuronal development.
Synonyms: JTK5A; D3S3195; RYK1; JTK5
Tractability: Small molecule: it belongs to a druggable protein family. Antibody: its Gene Ontology location is reachable by antibodies, with high confidence; UniProt predicts a signal peptide or a membrane-spanning region. PROTAC: ubiquitination databases record sites on it.
Gene: Protein-coding gene on chromosome 3 (134,065,303 to 134,250,929, reverse strand). Ensembl gene ENSG00000163785.
Subcellular location: Cell membrane; Nucleus; Cytoplasm
Subcellular location (Human Protein Atlas): Golgi apparatus; Cytosol
Pathways (Reactome):
Signal Transduction: PCP/CE pathway; TCF dependent signaling in response to WNT
Gene Ontology:
Molecular function: ATP binding; protein binding; protein tyrosine kinase activity; transmembrane signaling receptor activity; coreceptor activity; frizzled binding; protein kinase activity; transmembrane receptor protein tyrosine kinase activity; Wnt receptor activity; Wnt-protein binding
Biological process: positive regulation of MAPK cascade; protein phosphorylation; axon guidance; axonogenesis; canonical Wnt signaling pathway; cell surface receptor protein tyrosine kinase signaling pathway; chemorepulsion of dopaminergic neuron axon; commissural neuron axon guidance; corpus callosum development; midbrain dopaminergic neuron differentiation; neurogenesis; neuron differentiation; neuron projection development; non-canonical Wnt signaling pathway; positive regulation of cell proliferation in midbrain; positive regulation of neuron projection development; positive regulation of phosphatidylinositol 3-kinase/protein kinase B signal transduction; signal transduction; synapse assembly; Wnt signaling pathway, planar cell polarity pathway
Cellular component: cytoplasm; membrane; nucleus; plasma membrane; receptor complex
Genetic constraint (gnomAD): Loss-of-function variants: 8 observed, 31.58 expected, observed/expected ratio (o/e) 0.25, 90% interval 0.15 to 0.46. The upper end of that interval is the gene's LOEUF score, 0.46, which puts it in group 2 of 6, group 1 being the genes least tolerant of losing a copy. Missense variants: 302 observed, 387.89 expected, observed/expected ratio (o/e) 0.78, 90% interval 0.71 to 0.86. Synonymous variants: 142 observed, 141.53 expected, observed/expected ratio (o/e) 1, 90% interval 0.88 to 1.15.
Homologues: Orthologues: chimpanzee RYK (99% identical), macaque RYK (99% identical), pig RYK (96% identical), mouse Ryk (93% identical), dog RYK (91% identical), rat Ryk (90% identical), rabbit RYK (87% identical), guinea pig RYK (85% identical), tropical clawed frog ryk (82% identical), zebrafish ryk (75% identical), Caenorhabditis elegans lin-18 (30% identical). Paralogues in human: MST1R (25% identical), FGFR1 (25% identical), ROS1 (24% identical), MERTK (24% identical), AXL (24% identical), FGFR2 (24% identical), FGFR3 (24% identical), TIE1 (24% identical), DDR2 (24% identical), IGF1R (24% identical), FLT4 (24% identical), INSR (23% identical), and 41 more.
Diseases named in the same sentence as RYK in open-access papers:
RYK is named in the same sentence as 41 diseases in open-access papers, as found by Europe PMC text mining. Sharing a sentence is not in itself a finding about the gene and the disease. The quoted sentences say what the papers report.
glioma (10 papers, 2016 to 2023). A benign or malignant brain and spinal cord tumor that arises from glial cells (astrocytes, oligodendrocytes, ependymal cells). "In our univariate analysis, we observed a trend indicating that RYK expression was linked to improved survival outcomes in IDH mutant grade 2 gliomas cases." (PMID 37242509, 2023). "RYK expression has been linked to several human cancers, including glioma, ovarian, gastric, and prostate malignancies." (PMID 35204808, 2022). "Despite the complexity of these interactions, our findings demonstrate the potential prognostic value of RYK expression status in glioma patients." (PMID 37242509, 2023). "We conducted univariate and multivariate Cox regression analyses using publicly available TCGA and GEO datasets to investigate the impact of RYK gene expression status on glioma patient overall (OS) and progression-free survival (PFS)." (PMID 37242509, 2023). "We also examined TMZ-induced RYK gene expression profiles after 72 h by RT-qPCR in the glioma cell lines." (PMID 37242509, 2023). "Our results indicated that in IDH mutant gliomas, RYK expression and tumor grade were significant predictors of survival." (PMID 37242509, 2023). "To continue exploring the role of RYK in the regulation of TMZ response in glioma cells, we produced RYK knockdowns via siRNAs." (PMID 37242509, 2023). "To explore the role of RYK in regulation of TMZ response in glioma cells, we overexpressed RYK in a HEK293 cell line (AG) and a U138MG glioma cell line (AA) utilizing a lentiviral-based plasmid under a CMV promoter for transient transfection." (PMID 37242509, 2023). "Functional validation of RYK using lymphocytes and glioma cell lines resulted in gene expression analysis indicating differences in expression status between genotypes of the cell lines and TMZ dose response." (PMID 37242509, 2023). "RYK knockdown in glioma cells suppressed matrix metalloproteinase-2 (MMP2) and Wnt5a-induced invasion, suggesting RYK can regulate extracellular matrix degradation and tumor invasive capacity." (PMID 35204808, 2022). "In gastric cancer and glioma, RYK promotes cell migration and invasion whereas in prostate cancer Wnt5a-RYK have pro-apoptotic and pro-proliferative action." (PMID 36471440, 2022). "RYK facilitate the retaining of stemness and tumorigenic traits of glioblastoma multiforme and glioma cells, controlling its role via β-catenin signaling." (PMID 29108281, 2017). "Our results indicate that RYK expression could potentially function as a significant predictor or prognostic factor for the response and survival of glioma patients." (PMID 37242509, 2023). "Regarding the RYK knockdown and its effect on cell viability, it is possible that the reduced effect observed in the glioma cell line may be due to differences in the genetic and epigenetic backgrounds of glioma cells compared to HEK cells." (PMID 37242509, 2023). "The univariate Cox regression analysis revealed that RYK expression status (high vs. low, hazards ratio (HR) = 0.46; 95% confidence interval (CI), 0.23–0.94, p = 0.033) was a significant risk factor for OS in the IDH mutant TCGA glioma patient subgroup." (PMID 37242509, 2023). "According to our study, we suggest that RYK may provide an additional marker to guide glioma therapy." (PMID 37242509, 2023). "Thus, we examined expression levels of the 19 Wnt ligands, 10 FZDs and co-receptors, LRP6, receptor tyrosine kinase-like orphan receptor 2 (ROR2), and receptor-like tyrosine kinase (RYK) in glioma spheres." (PMID 27698350, 2016). "Our study has highlighted the intricate relationship between molecular biomarkers such as RYK expression and MGMT methylation and IDH mutant statuses, as well as their impact on patient survival outcomes in different types of gliomas." (PMID 37242509, 2023). "Our study aimed to evaluate the expression status of RYK as a predictor of time-to-event outcomes such as OS and PFS in glioma patients." (PMID 37242509, 2023).
glioma (continued). "RYK is one of the receptors for Wnt family member 5A (WNT5A) and has been reported to be involved in invasive activity in glioma-derived cells and to facilitate the pro-apoptotic and anti-proliferative effects of WNT5A in prostate cancer cells." (PMID 34437536, 2021). "In contrast, in the GBM, IDH wildtype TCGA glioma patient subgroup, RYK expression status was not a significant risk factor for OS." (PMID 37242509, 2023). "Overall, our findings suggest that RYK expression may serve as an important prognostic or predictor of TMZ response and survival for glioma patients." (PMID 37242509, 2023). "RMPAhigh gliomas were also enriched in the expression of ERBB2, FGFR1 and MET (and its ligand HGF), DDR2 (a receptor for activated collagen fibers), as well as the WNT co-receptors ROR1 and RYK." (PMID 27385209, 2016). "In addition, RYK, an atypical member of the receptor tyrosine kinase (RTK) family involved in the control of neuronal differentiation, resulted to be essential for WNT5a-dependent invasiveness in glioma, and its expression correlated with the WHO histological classification for glioma tissues." (PMID 29462960, 2018).
breast carcinoma (7 papers, 2012 to 2022). "A genetic variant of RYK has been associated with risk of breast cancer in humans, supporting the hypothesis that Ryk may be a candidate tumor promotion susceptibility gene." (PMID 24700353, 2014). "WNT/RYK signaling is described in numerous cancers including glioblastoma, melanoma, and breast cancer." (PMID 29930766, 2018). "Some ovarian- and breast cancer-derived cell lines are dependent on autocrine Wnts, suggesting that an inhibitory anti-RYK MAb may benefit a subset of patients with such tumors." (PMID 24058687, 2013). "Comprehensive overview of ligand (WNT1-16) and receptor (FZD1-10, LRP5-6, ROR1-2, RYK, PTK) genes and their implication in human breast cancer based on a survey of the primary literature." (PMID 32083079, 2020). "Evaluation of bRWD1 versus a similarly biotinylated fully human IgG1κ MAb, which recognizes a hapten not present in mammalian tissues, on a human breast cancer tissue microarray demonstrated expression of RYK on stroma and cancer cells in tumor cores." (PMID 24058687, 2013). "Based on the observations of active non-canonical WNT signaling in breast cancer tissue, we compared the expression levels of the known four non-canonical WNT co-receptors ROR1, ROR2, PTK7 and RYK in normal and cancerous breast tissue using the TNMplot database." (PMID 34911552, 2021). "Kinases BUB1, CHEK1, IRAK1, TTK, RYK, and VRK2, identified in this study, for example, have been reported to be highly overexpressed in ER-negative breast tumors and were critical for the growth of either ER-negative only or both ER-positive and -negative breast cancer cells." (PMID 22309939, 2012).
ovarian carcinoma (5 papers, 2013 to 2022). A malignant neoplasm originating from the surface ovarian epithelium. "RYK has been previously linked to ovarian cancer and brain tumors, but its role in the pathogenesis of GBM has been poorly investigated." (PMID 28086236, 2017). "RYK overexpression has been observed in human ovarian cancer and was correlated with decreased overall survival of patients." (PMID 24058687, 2013). "Although most of such data derive from in vitro models using cancer cell lines, in vivo experimental data supporting oncogenic roles for ROR2 have been reported in melanoma, renal cell carcinoma, ovarian cancer, and breast cancer, as well as for RYK in gastric and ovarian cancer." (PMID 34716856, 2022). "RYK (for related to tyrosine kinase) has been isolated from a DNA library of SKOV-3, an epithelial ovarian cancer cell line." (PMID 26328272, 2015).
prostate carcinoma (5 papers, 2018 to 2022). A carcinoma that arises from epithelial cells of the prostate gland. "Whether RYK amplification is a pathogenic variant in prostate cancer is currently unknown, however, RYK over-expression in mouse fibroblasts induces anchorage-independent growth in vitro and increases tumorgenicity in vivo, supporting an oncogenic role." (PMID 35204808, 2022). "Analysis of clinical prostate cancer genomic datasets indicates that RYK gene amplification occurs in 2–2.7% and 2.7–7.2% in primary and metastatic cases, respectively, indicating a higher frequency occurs in advanced disease." (PMID 35204808, 2022). "Extensive in vitro analyses revealed that the WNT5A receptors FZD5 and RYK mediate the anti-tumor effects of WNT5A on prostate cancer cells." (PMID 29930766, 2018). "Genes encoding FZD2-5, FZD8, VANGL1, ROR1, RYK, LGR4, LRP5 and 6, and GPC4 were highly expressed in at least three prostate cancer cell lines." (PMID 29717114, 2018). "In prostate cancer, RYK has been shown to be expressed in primary prostatic tissue and to be upregulated in DU-145 prostate cancer cells after antiestrogen treatment." (PMID 29930766, 2018). "Taken together, the data suggest a more prominent role of WNT5A/FZD5 than WNT5A/RYK signaling in prostate cancer." (PMID 29930766, 2018). "Interestingly, RYK upregulation was also reported in DU-145 prostate cancer cells in response to the anti-estrogen ICI 182,780, reflecting ER-β/Nf-κB signaling cross-talk and the presence of a cis-acting NF-κB binding element in the promoter region of RYK." (PMID 35204808, 2022). "By analyzing the expression of known WNT5A receptors in five different prostate cancer cell lines, performing functional assays, and validating receptor expression in a large set of human samples, we found the receptors FZD5 and RYK mediate anti-tumor effects of WNT5A in prostate cancer." (PMID 29930766, 2018). "In conclusion, WNT5A/FZD5 and WNT5A/RYK signaling are both involved in mediating the pro-apoptotic and anti-proliferative effects of WNT5A in prostate cancer." (PMID 29930766, 2018). "FZD7, FZD8, and ROR2 showed the lowest expression in most of the prostate cancer cell lines, while FZD6 and RYK were abundantly expressed." (PMID 29930766, 2018). "Therefore, we hypothesized that RYK may also act tumor diminishing in prostate cancer." (PMID 29930766, 2018). "Amongst all FZD receptors, FZD5 was one of the most highly expressed receptors in the prostate cancer cell lines and WNT5A also showed a stronger binding response to FZD5 than to RYK." (PMID 29930766, 2018). "Further correlation analysis with clinicopathological markers for prostate cancer revealed a significant correlation of FZD5 expression and the PSA level (r=0.01104, p=0.028) and between RYK-ICD and GS (r=0.1468, p=0.003)." (PMID 29930766, 2018). "In conclusion, this study suggests that FZD5 and RYK are the predominant receptors for mediating the pro-apoptotic and anti-proliferative effects of WNT5A in prostate cancer in vitro." (PMID 29930766, 2018). "RYK mRNA and nuclear RYK protein expression positively correlated with Gleason score, yet increased RYK expression alone does not appear to predict poor prostate cancer survival." (PMID 35204808, 2022). "Knockdown of RYK in PC-3 prostate cancer cells reduces Wnt5a-induced apoptosis in vitro without altering proliferation via an unclear mechanism." (PMID 35204808, 2022).
glioblastoma (4 papers, 2017 to 2023). The most malignant astrocytic tumor (WHO grade IV). "We found through overexpression and silencing experiments that the higher β-catenin level in the stem-like cells of glioblastoma is dependent upon RYK; in addition, knock-down of β-catenin strongly suppressed the stemness phenotype of GBM cells." (PMID 28086236, 2017). "In glioblastoma stem cells, RYK is overexpressed, is required for the activation of the pluripotency-related transcription-factor circuitry, and sustains neurosphere formation, leading to the establishment and maintenance of an undifferentiated state." (PMID 28086236, 2017). "Moreover, RYK is upregulated in the glioblastoma stem cells, which is essential for the stimulation of the pluripotency-relevant transcription-factor circuitry, and supporting neurosphere formation, resulting in an in-distinguished condition." (PMID 29108281, 2017). "The potential role played by RYK in cancer is, at the moment, not well defined, but there are a few studies demonstrating increased RYK expression in some tumor models, such as glioblastoma, acute lymphoblastic leukemia and acute myeloid leukemia and others." (PMID 36980592, 2023).
gastric cancer (3 papers, 2020 to 2022). A primary or metastatic malignant neoplasm involving the stomach. "RYK was also positively correlated with gastric cancer tumorigenesis and the potential of liver metastasis." (PMID 35715770, 2022).
leukemia (3 papers, 2021 to 2024). A malignant (clonal) hematologic disorder, involving hematopoietic stem cells and characterized by the presence of primitive or atypical myeloid or lymphoid cells in the bone marrow and the blood. "The qRT-PCR and ELISA results of this study reflected that the hub genes RHOA, RYK, NLK and MHC-I molecules HLA-A of the atypical Wnt signaling pathway were down-regulated in leukemia cells." (PMID 38962268, 2024).
lung carcinoma (3 papers, 2011 to 2023). "RYK expression has also been associated with tyrosine kinase inhibitor drug tolerance and resistance in lung cancers, and BRAF inhibitor resistance in melanomas." (PMID 37242509, 2023). "In lung cancer, RYK promotes resistance acquired upon EGFR inhibition." (PMID 36471440, 2022).
melanoma (3 papers, 2018 to 2023). A malignant, usually aggressive tumor composed of atypical, neoplastic melanocytes. "In particular, WNT11-cognate receptor FZD7 and its co-receptor RYK were both consistently upregulated in metastatic melanomas in most of the studies." (PMID 33082334, 2020).
brain tumors (2 papers, 2015 to 2017). "Pediatric brain tumors derived from neuroepithelial precursor cells express RYK." (PMID 26328272, 2015).